GFOD2 (Gfo/Idh/MocA-like oxidoreductase domain containing 2)
Description:
Promotes matrix assembly.
Synonyms: FLJ23802; MGC11335
Tractability: Antibody: UniProt places it where antibodies can reach, with medium confidence; UniProt predicts a signal peptide or a membrane-spanning region; its Gene Ontology location is reachable by antibodies, with medium confidence. PROTAC: ubiquitination databases record sites on it; its protein half-life has been measured.
Gene: Protein-coding gene on chromosome 16 (67,674,531 to 67,719,339, reverse strand). Ensembl gene ENSG00000141098.
Subcellular location: Secreted, extracellular space, extracellular matrix
Subcellular location (Human Protein Atlas): Nucleoplasm; Cytosol; Predicted to be secreted
Gene Ontology:
Molecular function: nucleotide binding
Biological process: extracellular matrix organization
Cellular component: extracellular matrix
Genetic constraint (gnomAD): Loss-of-function variants: 9 observed, 25.63 expected, observed/expected ratio (o/e) 0.35, 90% interval 0.21 to 0.61. The upper end of that interval is the gene's LOEUF score, 0.61, which puts it in group 2 of 6, group 1 being the genes least tolerant of losing a copy. Missense variants: 476 observed, 547.92 expected, observed/expected ratio (o/e) 0.87, 90% interval 0.81 to 0.94. Synonymous variants: 211 observed, 232.43 expected, observed/expected ratio (o/e) 0.91, 90% interval 0.81 to 1.02.
Homologues: Orthologues: chimpanzee GFOD2 (99% identical), dog GFOD2 (98% identical), rabbit GFOD2 (98% identical), guinea pig GFOD2 (97% identical), pig GFOD2 (97% identical), mouse Gfod2 (96% identical), rat Gfod2 (77% identical), tropical clawed frog gfod2 (72% identical), zebrafish gfod2 (61% identical), Drosophila melanogaster CG17712 (45% identical). Paralogues in human: GFOD1 (63% identical), DHDH (16% identical), BLVRA (12% identical).
Diseases named in the same sentence as GFOD2 in open-access papers:
GFOD2 is named in the same sentence as 10 diseases in open-access papers, as found by Europe PMC text mining. Sharing a sentence is not in itself a finding about the gene and the disease. The quoted sentences say what the papers report.
coronary disease (1 paper, 2022). "Variants in GFOD2 have also been linked to the metabolic system and coronary disease, e.g., levels of circulating lipid levels and differential response to cholesterol-lowering diet." (PMID 35477560, 2022).
schizophrenia (1 paper, 2022). A major psychotic disorder characterized by abnormalities in the perception or expression of reality. "SNPs in the GFOD2 have been associated with schizophrenia related phenotypes and a recent study using a zebrafish model revealed its implication in the developing and adult brain as well as GFOD2 expression in a subset of inhibitory GABA-neurons." (PMID 35477560, 2022).
Sepsis (1 paper, 2025). Sepsis is defined as life-threatening organ dysfunction caused by a dysregulated host response to infection. "Integrating WGCNA with three machine learning algorithms, we identified six diagnostic genes—PGM3, GDF15, GART, GFOD2, E2F2, and ATP1B2—associated with sepsis-induced ALI, which were validated in clinical samples by Western blotting." (PMID 41142807, 2025).
tumour (1 paper, 2020). "All five genes in the module (AL121899.1, GFOD2, SPINK8, C2orf54 and CST6) were down‐regulated and lost positive correlations with their neighbours in tumour samples." (PMID 32164040, 2020).
GFOD2 also shares sentences with these, for which no sentence is quoted: chronic kidney disease (1 paper); diabetes (1); Hypercholesterolemia (1); Hypertension (1); Obesity (1); preeclampsia (1).